PGAP3 (post-GPI attachment to proteins phospholipase 3)
Diseases named in the same sentence as PGAP3 in open-access papers (continued):
Sharing a sentence is not in itself a finding about the gene and the disease.
ovarian serous cystadenocarcinoma (1 paper, 2023). A malignant serous cystic epithelial neoplasm arising from the ovary. "The top five interacting genes were selected for analysis, and the results showed that PGAP3, GRB7, STARD3, and PSMD3 had a significant positive correlations with STAT3 in TCGA cancers, such as ovarian serous cystadenocarcinoma (OV)." (PMID 36977736, 2023).
rheumatoid arthritis (1 paper, 2018). A chronic, systemic autoimmune disorder characterized by inflammation in the synovial membranes and articular surfaces. "In our study, there were six novel loci outside of this region where genetic variation may influence rheumatoid arthritis risk via changes in DNA methylation (TTC34, MMEL1, AFF3, IRF5, CXCR5 and PGAP3)." (PMID 29893838, 2018).
viral infection (1 paper, 2025). "Accordingly, PGAP3 (SNP rs2941504) was highly expressed in innate and adaptive immune cell types relevant to abating viral infection as B cell, natural killer (NK) cells, T cells, monocytes, and alveolar and interstitial macrophages." (PMID 40867500, 2025).
cancer (11 papers, 2015 to 2025). A tumor composed of atypical neoplastic, often pleomorphic cells that invade other tissues. "Validating these antibodies is also important since GRB7 and PGAP3 may themselves serve as important genes for tumor biology in breast and other cancers." (PMID 37809181, 2023). "PGAP3 has also been involved in tumorigenesis and cancer progression." (PMID 36430456, 2022). "Thus, the coexpression pattern between ERBB2 and other genes, such as PGAP3, STARD3, and PNMT, may be a marker of cancer, and site mutations in the interaction anchors or dysregulation in interactions related to ERBB2 may be a new target for cancer studies." (PMID 36702236, 2023). "These included multitrait colocalization at 6 loci with a consistent direction of effect between CAD and cancer (ABO, PGAP3, ANGPTL4, SREBF1, HAUS6, and SYNJ2BP) and 7 with an opposing direction (CDKN1A, RGS19, CALCRL, SF3A3, LAMC1, MYO9B, and MIA3)." (PMID 40874306, 2025). "In addition, studies have shown that PGAP3, GRB7, STARD3, and PSMD3 are significantly positively correlated with STAT3 in TCGA cancers; however, reports on these are lacking." (PMID 36977736, 2023).
tumor (9 papers, 2016 to 2026). "The overexpression of circ-PGAP3 improves the poor prognosis of CC and significantly inhibits cell proliferation in vitro and tumor growth in vivo." (PMID 36142352, 2022). "The data indicate that DNA methylation (MGMT) and malfunction of GPI anchoring (PGAP3) are distinct mechanisms that are relevant for tumor progression and relapse." (PMID 34529172, 2022). "The overexpression of PGAP3 and MIEN1 has been linked to metastasis in BC patients, suggesting that they could be therapeutic targets for combating tumor spread." (PMID 40136626, 2025). "Boyden chamber assay revealed that the tumour cells transfected with siPGAP3‐189 resulted in a greater decrease of invasion through the Matrigel, compared with the normal cells (NC), indicating that PGAP3 depletion decreased the invasive capabilities of GC cells." (PMID 37386793, 2023). "Co‐overexpression of the PGAP3 and ERBB2 was correlated with T stage, TNM stage, tumour size, intestinal histological type and poor survival proportion in 141 GC patients." (PMID 37386793, 2023). "As expected, co‐overexpression of PGAP3 and ERBB2 was also correlated with T stage (*p = 0.01), TNM stage (*p = 0.032), tumour size (*p = 0.032) and Lauren classification (**p = 0.008)." (PMID 37386793, 2023). "These sites were annotated to genes involved in diverse biological pathways, including neurological development (AHNAK, PGAP3), lymphocytic function (ITGAL), apoptosis (RELT), tumor suppression (ZGPAT), and endothelial-to-mesenchymal transition (PRSS23)." (PMID 32084330, 2020). "However, tumor tissue and sequencing patterns would be necessary to properly investigate the effect of MGMT expression (and PGAP3, respectively) on actual prognosis for the separate TCGA subtypes." (PMID 34529172, 2022).
infection (1 paper, 2025). The state of being infected such as from the introduction of a foreign agent such as serum, vaccine, antigenic substance or organism. "Indeed, knockdown of PGAP1 or PGAP3 with shRNAs could not inhibit Echo7 infection." (PMID 41252368, 2025).
PGAP3 also shares sentences with these, for which no sentence is quoted: allergic asthma (2 papers); breast tumor (2); cervical cancer (2); genetic diseases (2); glaucoma (2); intellectual disabilities (2); neurological disorder (2); prostate carcinoma (2); atopic dermatitis (1); Autoimmunity (1); bacterial infection (1); colorectal cancer (1); corpus callosum agenesis (1); Crohn disease (1); esophageal cancer (1); hyperphosphatemia (1); Macrotia (1); mucinous tumor (1); neural tube defect (1); neurodevelopmental disorder (1); Seizure (1); Synthesis (1); triple-negative breast carcinoma (1).